SNORD124 (small nucleolar RNA, C/D box 124)
Gene: Small nucleolar RNA gene on chromosome 17 (40,027,542 to 40,027,645, reverse strand). Ensembl gene ENSG00000238793.
Gene Ontology:
Biological process: RNA processing
Cellular component: nucleolus
Homologues: Orthologues: chimpanzee SNORD124 (100% identical), macaque SNORD124 (99% identical), pig SNORD124 (89% identical), rabbit SNORD124 (85% identical), mouse Gm22059 (84% identical), rat Snord124 (84% identical), guinea pig SNORD124 (81% identical).